MYCN (MYCN proto-oncogene, bHLH transcription factor)
Diseases named in the same sentence as MYCN in open-access papers (continued):
Sharing a sentence is not in itself a finding about the gene and the disease.
tumor (continued). "Here we investigated if Syk is an immune-oncology target in NB and tested whether a novel immunotherapeutic approach utilizing Syk inhibitor together with radiation and ICB could provide a durable anti-tumor immune response in an MYCN amplified murine model of NB." (PMID 37350973, 2023). "Therefore, immunohistochemical staining for MYCN might be used as a screening method to identify this tumor subtype, although gene amplification should be confirmed using other methods, such as FISH analysis." (PMID 38074692, 2023). "Taken together, this information indicates that the upregulation of TNFAIP3 induced by BGA002 could be involved in the inhibition of the inflammation and in the restoration of the Th1/M1 susceptibility in MYCN-related SCLC and NB, leading to anti-tumor immunity restoration." (PMID 36765949, 2023). "Although tumors in children present a low mutational rate in comparison to adult neoplasms, specific chromosomal aberrations (1p and 11q loss and 17q gain), mutations in certain genes (ALK, PHOX2B, ATRX, and TERT), and amplification of the MYCN oncogene are linked to NB tumorigenesis and outcome." (PMID 37760568, 2023). "The contribution of exosomes to the biology of NB may be understood better in light of the molecular content and secretion dynamics of these vesicles and how these may differ in NB tumours with aggressive phenotypes similar to that predicted for MYCN-amplified NB." (PMID 36362869, 2022). "Therefore, MYCN gene may regulate the expression of key genes in the process of tumor metabolism, cycle, apoptosis, immunity and so on through the highly expressed N-myc protein." (PMID 36311753, 2022). "In addition MYCN amplification should be evaluated both in the primary tumor and BM metastases although the tumor may show genetic heterogeneity." (PMID 34558657, 2022). "We also put into context the utility of tumour-derived exosomes and cfDNA for detecting crucial alterations to ALK and MYCN genes in NB patient primary and relapse samples, while comparative studies of the diagnostic accuracy of tumour-derived exosomes and cfDNA are still largely lacking." (PMID 36362869, 2022). "MYCN facilitates NB growth in complex microenvironments with limited nutrient availability by overriding hypoxia-inducible factor (HIF1α)-mediated cell cycle arrest and promoting intratumoral vascular development to facilitate nutrient access by interior tumor regions." (PMID 35764645, 2022). "This view could be extended to the MYCN and ALK oncogenes, because they are frequently mutated in NB, have a well-established influence on TME, and are pivotal targets of clinically evaluated anti-tumor therapies." (PMID 36231134, 2022). "We have previously demonstrated that MYCN-amplified NB cells depend on lipid metabolism, since targeting both fatty acid β-oxidation as well as de novo fatty acid synthesis resulted in reduction of tumor burden and the latter also induced neuronal differentiation." (PMID 35850708, 2022). "However, we cannot decipher whether it results of MYCN direct effect on HLA-gene expression in tumor cells, or from an indirect effect due to CCL2 downregulation, resulting in low immune cell infiltration and inflammation." (PMID 36923280, 2022). "However, spontaneous regression does not occur in older children or in high-risk tumours with characteristics such as MYCN amplification or Anaplastic Lymphoma Kinase (ALK) mutation." (PMID 36263020, 2022). "The ADRN tumor cells could be further divided into MYCN-amplified, MYCN non-amplified high-risk, and MYCN non-amplified low-risk." (PMID 35362827, 2022). "However, in our population, the female:male ratio is 1:2, only one patient with CNS at diagnosis had liver metastasis and only one was affected by tumor-carrying MYCN amplification; on the other hand, all patients had diffuse metastatic disease with skull involvement at diagnosis." (PMID 36551734, 2022).
tumor (continued). "C1GALT1 high expression is an independent prognostic factor for better survival outcomes in NB patients, and could provide complementary prognostic information in addition to age of patients, differentiation status of tumor, MYCN amplification status, and clinical stages." (PMID 35169131, 2022). "However, the expression of the MYCN protein was low in tumor tissues." (PMID 36016998, 2022). "Other factors than tumor biology (like treatment) may influence outcome within the different subgroups (risk group/MYCN status); however, the limited number of patients did not allow us to study those." (PMID 35688160, 2022). "We also found that DNA methylation of enhancer regions was enriched in group A-related methylation probes, suggesting that MYCN amplification may play a role in dynamic changes in DNA methylation status in NBs, thereby leading the tumor cells to acquire an aggressive character." (PMID 36572864, 2022). "Since the initial discovery of MYCN, many prognostic biomarkers have been proposed for NB, with the most intensive studies including histopathologic classification, tumor staging, MYCN amplification, tumor cell DNA index (ploidy), and segmental chromosomal aberrations." (PMID 36211401, 2022). "Moreover, while MYCN drives a tumor immunosuppressive environment, which impacts survival in several MYCN-positive tumors, the block of MYCN by the anti-MYCN BGA002 is able to reactivate and restore the effectiveness of the natural killer immune cells against NB." (PMID 35890348, 2022). "However, MYCN regulation of the molecular clock and its effects on tumor phenotype remain largely unknown." (PMID 34183658, 2021). "In support of our finding, mechanisms other than MYC/MYCN downregulation contribute to BETi activity, because inhibition of cell proliferation has been reported even with no reduction, or even an increase, of these transcription factors in lines from different tumor types." (PMID 33668642, 2021). "Interestingly, when each individual group of IDRFs was analyzed, we found that tumor infiltration into adjacent organs or structures was associated with MYCN amplification and high MKI, and that tumor vascular encasement was associated with grade of neuroblastic differentiation." (PMID 33314708, 2021). "Heterogeneity could be confirmed by FISH analysis (MYCN and telomere probe) of one relapsed tumor." (PMID 33627664, 2021). "Indeed, the RetM919T mouse also results in NB tumor development when combined with Th-MYCN." (PMID 33921066, 2021). "Thus, we postulate that MYCN-mediated repression of the clock could induce the unconstrained expression of lipogenic genes and activate lipid metabolism to support tumor growth." (PMID 34183658, 2021). "Thus, we hypothesized that the loss of Rb1 would synergize with MYCN overexpression to reshape the N-Myc cistrome and drive tumor progression." (PMID 34099734, 2021). "This inverse correlation between deletion of 11q locus and MYCN focal gain could be due to their common effect in NB pathogenesis: both can disrupt microRNA let-7, which is considered to possess a fundamental role in tumour development." (PMID 34884690, 2021). "Thus, the higher plasma MYCN/NAGK ratio indicated heavier tumor burden in NB patients." (PMID 32896084, 2020). "Additionally, more work is needed to understand how the decrease in MYCN expression seen after local dinutuximab therapy might contribute to improved tumor response." (PMID 32096344, 2020). "In addition, the expression of MYCN in tumor xenograft was detected by qRT-PCR." (PMID 32857725, 2020).
tumor (continued). "Thus, tissue-specific enhancers are a determinant of MYCN amplicon structure and may be required for MYCN expression in various tumor entities." (PMID 33199677, 2020). "Indeed, MYCN overexpression is sufficient to induce neuroblastic tumor formation in mice." (PMID 33199677, 2020). "Interestingly, ATRX mutations and MYCN amplification have never been observed in the same NB tumor, suggesting a potential synthetic lethal condition." (PMID 33628735, 2020). "In contrast, a ‘hot” MYCN-NA tumor without targetable mutation may be better treated with a combination of chemotherapy and an immune checkpoint inhibitor or TGF-β inhibitor to prevent immune escape." (PMID 33050533, 2020). "However, the primary tumor site of all patients with MYCN amplification was in the abdomen." (PMID 31685009, 2019). "While MYCN amplification status was available for each tumor sample, ALK mutation status was not." (PMID 30952905, 2019). "Hence, it is most effective in inducing differentiation in tumours with high MYCN expression." (PMID 31235824, 2019). "Since several evidences suggest a causal role of MYCN in the development of NB and in other tumor types, while its expression is negative in normal tissues, MYCN oncogene may represent an attractive cancer therapeutic target." (PMID 31040907, 2019). "MYCN amplification, activating mutations in the ALK receptor tyrosine kinase, TERT rearrangements, inactivating ATRX mutations and dominant negative mutations in PHOX2B are among the most recurrent genetic events that drive oncogenic signaling and tumor formation." (PMID 30952905, 2019). "In multivariable analysis, increment in every unit of UCHL1 mRNA correlated with a decrease in HR for OS (HR: 0.338, 95% CI: 0.116–0.980, P = 0.046) and EFS (HR: 0.476, 95% CI: 0.228–0.994, P = 0.048) independent of established risk markers (MYCN status, tumor stage and patient age at diagnosis)." (PMID 30359286, 2018). "Interestingly, this tumor showed complex genome rearrangements and focal amplification of MYCN." (PMID 30420702, 2018). "This may indicate that without MYCN amplification more total mutations (and thus greater deviation from a normal gene expression profile) are required for MYCN-NA tumor to progress to advanced disease." (PMID 28871274, 2017). "However, U251-MGmycN/Survivin cells formed significantly bigger spheroids in 2D culture and significantly more and bigger colonies in soft agar when compared to U251-MGmycN/C cells as depicted for cells from tumor #2 containing mycN and Survivin transgenes and from tumor #19 containing mycN alone." (PMID 29282022, 2017). "Moreover, a recent report described less apoptosis in tumors and decreased survival of mice transplanted with immortalized embryonic rat fibroblast transduced with tumor-promoting mycN and Survivin when compared to mice with transplanted tumors genetically engineered only with Survivin or mycN." (PMID 29282022, 2017). "Importantly, the INRG moves towards a more molecular and genetic classification of disease, incorporating such additional measurements as general tumor ploidy, chromosome 11q aberration, and classification of MYCN amplification as focal or diffuse in the tumor population." (PMID 28035989, 2016). "An alteration in the tumor biology, such as the de novo observed MYCN amplification and 1p deletion, may have broken immunologic tolerance and generated antibodies against NB-expressed antigens, also expressed in the hippocampi (causing LE) and the myenteric plexus (producing CIPO)." (PMID 27385747, 2016). "Therefore, we checked, whether tumor growth depended on MYCN function by JQ1 and MLN8237 in xenografts and in cell lines." (PMID 27769070, 2016). "When high-risk tumours with MYCN amplification were compared to high-risk tumours without MYCN amplification, higher levels of β-catenin were found in high-risk tumours without MYCN amplification." (PMID 25266063, 2015).
tumor (continued). "Of note, this tumour was not harbouring any IDH1/2 mutation or MYCN amplification." (PMID 26399631, 2015). "In an earlier study, we used SNP arrays to analyse tumours from patients who had received pre-operative chemotherapy under International Society of Paediatric Oncology (SIOP) protocols, and noted an apparent association between MYCN gain and the high risk diffuse anaplastic subtype." (PMID 25749049, 2015). "MYCN expression was undetectable in GI-ME-Nkd-3650, GI-ME-Nkd-1463 and GI-ME-Nkd-LacZ cells by Western Blotting and real-time quantitative PCR, thus further corroborating the conclusion that the tumor promoting effect of ATM silencing in the NB cell background does not require MYCN." (PMID 26053094, 2015). "Similarly, MYCN expression was shown to drive tumor development from a neural crest cell line." (PMID 26222553, 2015). "Additionally, since MYCN-amplified tumours appear less differentiated, the smaller size of their NT may represent tubules in these tumours being less well-developed." (PMID 24679140, 2014). "Therefore, MIBG and phenformin can be tumor-targeting MYC/MYCN destabilizing agents in NB." (PMID 24190252, 2014). "In addition, this tumor shows a MYCN as well as an ALK amplification." (PMID 25161957, 2014). "This implies that the tumor vasculature in the Th-ALKF1174L/Th-MYCN mice may be more mature." (PMID 24667968, 2014). "In addition, a focal gain of this locus was found in one MYCN amplified primary tumor sample." (PMID 23308108, 2013). "We could not find this suggested correlation in either our clinical patient material including several tumor samples with MYCN amplification, or cell lines derived from high-risk patients with or without MYCN amplification." (PMID 22276108, 2012). "In this set, we compared not only MYCN-nonamplified vs MYCN-amplified tumours, localised stages vs stage 4 vs stage 4S, patients below 1 vs above 1 year, but also high vs low-risk tumours according to a highly accurate gene expression-based classification using the PAM algorithm." (PMID 19707195, 2009). "Pair-wise comparison analysis was performed initially for 20 primary infant NB tumours diagnosed at < 12 months; owing to the small number of cases, stage 4 NB were analyzed together without distinction of MYCN gene status (8 stage 4s and 12 infant stage 4, including 5 MYCN amplified cases)." (PMID 19192278, 2009). "Recently, amongst unfavorable NB tumours, two major genetic subtypes have been described: advanced stage NB without MYCN amplification, with high 11q LOH directly associated with 14q deletion, but inversely correlated with tumours with MYCN amplification and 1p36 allelic loss." (PMID 19192278, 2009). "Although both ATUX-1215 and ATUX-5800 affected MYCN at the protein and gene level in vitro, we noted that ATUX-1215 was the better anti-tumor compound in vivo." (PMID 41539997, 2026). "DNA methylation profiling revealed MES subtype as the predominant molecular tumor subtype (37.4%), followed by RTK I (30.4%), RTK II (23.8%), and others (8.4%; MYCN, midline, H3 G34 mutant, H3 K27-altered)." (PMID 41597253, 2026). "Spinal ependymal tumors are a diverse group of neoplasms encompassing four subtypes: spinal ependymoma (SP-EPN), spinal ependymoma, MYCN-amplification (SP-EPN-MYCN), spinal myxopapillary ependymoma (SP-MPE), and spinal subependymoma (SP-SE)." (PMID 41160379, 2025). "Indeed, emerging evidences have shown that MYCN drives an immunosuppressive environment, including reduced natural killer (NK) cell cytotoxicity, dysfunctional T‐cell profile, and immunosuppressive myeloid population, these impair anti‐tumor immunity and impact NB patient survival." (PMID 40600620, 2025). "The gene expression of ketolytic enzymes BDH1, OXCT1 and ACAT1 were analysed in the context of MYCN amplification, INSS tumour stage progression and overall event free survival." (PMID 41420301, 2025).
tumor (continued). "miR-204 is particularly pivotal, where it acts as a tumour suppressor in NB by directly targeting both PHOX2B and MYCN." (PMID 40779030, 2025). "MYCN is upregulated in HCC cells and tumor tissues from patients with HCC and is correlated with the recurrence of de novo HCC." (PMID 40027135, 2025). "We identified a primary tumour sample with two distinct subclones (MB272), harbouring MYC (C3) and MYCN (C2) amplifications simultaneously." (PMID 40335697, 2025). "DNA methylation analysis classified the tumor within the SP-EPN-MYCN subgroup, indicating the shared function between MYC and MYCN." (PMID 40365336, 2025). "Chromatin loop analysis identified 4,168 HB-specific and 4,009 non-tumor-specific chromatin interactions, anchoring 187 DEGs, including TRIB2, SERPINE2, and MYCN." (PMID 41462308, 2025). "In NB tumours with MNA, telomere maintenance is commonly achieved through re-expression of TERT, which is promoted by direct binding of MYCN to the E-box consensus sites within the TERT promoter region." (PMID 40713849, 2025). "Compact tumor organoids exhibited a higher expression of genes involved in WNT-mediated maintenance of nephron progenitors (e.g. LGR5, MYCN, HMGA2, LIN28B, NCAM, WNT4, BMP7)." (PMID 39740515, 2025). "Using our transgenic MYCN/ALKF1178L model, we found that once tumor cells developed indisulam resistance, they predominantly acquired SCP features seen during normal adrenal medulla development." (PMID 40962798, 2025). "This inhibition is accompanied by the modulation of pro- and anti-apoptotic proteins BAX and BCL-2, a reduction in MYCN mRNA expression, and a decrease in TNF-α secretion, suggesting a direct impact on tumor growth and cell survival." (PMID 40942095, 2025). "Most importantly, these enable the distinction of VHR tumor groups (canonical MYC and MYCN-amplified SHH) in which all current therapies (conventional chemotherapy and CSI) are ineffective." (PMID 39377358, 2025). "Further, there was a highly significant correlation between an amplified MYCN gene, and levels of PRMT5 and E2F1 gene expression in the tumour tissue." (PMID 39021294, 2025). "MYCN, or N-Myc, is a member of the MYC family of transcription factors, which plays a key role in tumor formation by regulating genes involved in proliferation, differentiation, and apoptosis." (PMID 40365336, 2025). "The expression of glycolytic genes HK2, GAPDH and ENO1 were analysed in the context of MYCN amplification, INSS tumour stage progression and overall event free survival using KM plots." (PMID 41420301, 2025). "In ASTROs PNC, only one tumour showed a homozygous CDKN2A/B deletion, whilst MYCN amplifications and RB1 alterations were frequently observed." (PMID 39899075, 2025). "The metabolic symbiosis phenomenon describes how tumour cells switch between aerobic glycolysis and OXPHOS, depending on the tumour microenvironment (TME) and amplified oncogenes such as MYCN." (PMID 41440947, 2025). "Consistent with impaired photoreceptor differentiation observed in MYCN-driven tumors, CRX expression was undetectable within these tumor tissues." (PMID 40943594, 2025). "The 6-week-old Th-MYCN+/− SMG was selected based on observed macroscopic tumors post-dissection, establishing it as a positive control for tumor growth." (PMID 40580553, 2025). "To verify whether monocyte- and macrophage-CM modulate the tumor plasticity of SCC cells, we analyzed the expression of genes associated with epithelial-mesenchymal transition (EPCAM, SOX2), stemness (NANOG, MYC, EZH2), and neuroendocrine differentiation (CHGA, AURKA, MYCN)." (PMID 41259557, 2025). "Similar anti-tumor activity is observed in NGP and COG-N-424x xenografts, ALK WT models with varying levels of ALK overexpression and MYCN status, as observed in patient tumors." (PMID 40813394, 2025). "Only a small number of tumor cells are required, compared with primary tumor biopsies, and FISH is more sensitive by counting the MYCN copy number in each single cell." (PMID 39049899, 2024).